CCR2 (C-C motif chemokine receptor 2)
Diseases named in the same sentence as CCR2 in open-access papers (continued):
Sharing a sentence is not in itself a finding about the gene and the disease.
pancreatic cancer (continued). "Disrupting this axis by targeting CCR2 or CCL2 has resulted in reduced mobilization of inflammatory monocytes from the bone marrow and peripheral blood to tumour sites, which correlated with increased survival and decreased tumour burden in mouse models of lung metastasis and pancreatic cancer." (PMID 28210073, 2017). "Moreover, in pancreatic tumours, targeting TAMs by inhibiting either the myeloid cell receptors colony-stimulating factor-1 receptor (CSF1R) or chemokine (C-C motif) receptor 2 (CCR2) decreased the number of tumour-initiating cells (TIC) and inhibited metastasis." (PMID 29065107, 2017). "Additionally, PF-04136309, a small molecule CCR2 inhibitor, depletes CCR-2+/CD14+ monocytes and macrophages from the primary pancreatic tumor and premetastatic liver resulting in enhanced anti-tumor immunity, decreased tumor growth, and reduced metastasis in mice model." (PMID 27191744, 2016). "Notably, the inhibition of CCR2 using the small-molecule CCX872 improved the therapeutic benefits of anti-Programmed cell death protein 1 (PD-1)/Programmed cell death protein ligand 1 (PD-L1) immunotherapy in a syngeneic, orthotopic mouse model of pancreatic cancer." (PMID 34575965, 2021).
COVID-19 (65 papers, 2020 to 2025). A disease caused by infection with severe acute respiratory syndrome coronavirus 2. "In other studies, direct associations between CCR2 expression levels in PBCs and COVID-19 severity were detected." (PMID 36009555, 2022). "Severe COVID-19 associated with CCR2 genetic variants that predict high expression of CCR2 in lung tissue." (PMID 36009555, 2022). "In a genome-wide association study of critical illness in COVID-19, a CCR2 variant predicted to increase expression in the lung was identified." (PMID 33553478, 2021). "This study showed that interferon α and β receptor subunit 2 gene (IFNAR2), tyrosine kinase 2 gene (TYK2) and chemokine receptor type 2 gene (CCR2) gene were associated with severity of COVID-19." (PMID 33396837, 2020). "We therefore predict that each of the CCR2 and CCR5 receptors has a complementary role in infection-associated inflammation and tissue sequelae in COVID-19 with CCR2/CCL2 seen in both early and late stages of infection and CCR5/CCL5 seen later in the infectious process." (PMID 35749425, 2022). "Furthermore, a recent genome-wide association study analysis identified a polymorphism in the CCL2 receptor (CCR2) as associated with critical COVID-19 illness." (PMID 34471264, 2021). "CCR2 can have a protective activity in the early phase of mouse-adapted SARS-CoV2 infection." (PMID 36433939, 2022). "Furthermore, in lung tissues, transcriptome-wide association demonstrated that predicted low levels of CXCR6 together with low expression of CCCR3 and high expression of CCR2 are associated with severe COVID-19 (defined as admission to critical care) vs. controls." (PMID 33807915, 2021). "Corresponding proteins from many of these DEGs have already been identified as drug targets for the treatment of various diseases such as COVID-19, asthma or rheumatoid arthritis (e.g., CCR2, CCR3, CXCL8, JAK3, HRH, CA4, see clinicaltrials.gov)." (PMID 38242945, 2024). "Evidence suggests that an involvement of CCL2 and its receptor (CCR2) is involved in the collection of monocytes and the infusion of these cells into the lungs of COVID-19 patients." (PMID 38803488, 2024). "CCR2 expression is increased in severe COVID-19, and hsa-miR-1291 has also been identified as a potential early biomarker of COVID-19 severity." (PMID 36593971, 2023). "Gene expression differences between COVID-19 patients and healthy controls revealed that CCR2, CXCL10, I-κB, NF-κB and Nrf2 were significantly upregulated when analyzing the log2fold change expression values, the iNOS gene showed tendencies." (PMID 37832397, 2023). "Of these genes, 7 are chemokine receptor genes (CCR1, CCR2, CCR3, CCR5, CCR9, CCRL2, and CXCR6), which are likely linked to the segment’s association with COVID-19 severity." (PMID 36763080, 2023). "Six genes (namely, SLC20A6, CCR9, CXCR6, CCR2, CCR5, and CCR5AS) were significant from the MR-JTI analysis after Bonferroni correction, indicating causal support for these genes on COVID-19 hospitalization." (PMID 35318325, 2022). "CCR2 (encoding CC chemokine receptor type 2) and TYK2 (encoding tyrosine kinase 2) were identified as genetic mediators of COVID-19 critical illness in an unbiased search of genetic mechanisms behind this phenotype to identify causal variants." (PMID 36009555, 2022). "PBCs CCR2 mRNA levels were similar in COVID-19 patients and control subjects when all patients were considered but were greater in critical patients as compared to controls or less severe patient groups (one-way ANOVA, post-hoc analysis)." (PMID 36009555, 2022). "An increased CCR2 expression has been reported in patients with severe COVID-19, and similarly, hsa-miR-1291 has been pinpointed as a potential early biomarker of COVID-19 severity." (PMID 35130828, 2022). "This review describes the role of the CCL2/CCR2 and CCL5/CCR5 chemokine pathways associated with amplification of inflammatory responses in COVID-19 and the role of CVC in inhibiting this pathway." (PMID 35749425, 2022).
COVID-19 (continued). "Both CCR1 and CCR2 interact with pro-inflammatory chemokines which are upregulated in the lungs of severe COVID-19 patients." (PMID 36433939, 2022). "Given this, investigations into CVC as a dual CCR2/5 functional antagonist offer a unique rationale for the potential treatment of COVID-19." (PMID 35749425, 2022). "The I-SPY-COVID-19 Trial is investigating the clinical utility of cenicriviroc against macrophage attractant chemokine molecules designated CCR-2 and CCR-5." (PMID 35456177, 2022). "Conversely, post-COVID-19 subjects had normal proportions of monocyte subsets which had returned to a normal basal resting state and expressed the highest CCR2, CCR5, CD86 and HLA-DR levels on their surface." (PMID 34572439, 2021). "CCR2 was found to be expressed at higher levels in COVID-19 patients than controls in all monocyte and DC subpopulations except pDCs." (PMID 34614036, 2021). "In addition, the expression of CCR1 and CCR2 was reduced in peripheral blood monocytes from COVID-19-recovered patients." (PMID 39811276, 2025). "Understanding the role of CCR2 in the context of post-COVID-19 immune dysregulation may provide new insights into potential therapeutic targets." (PMID 39768836, 2024). "Through its receptor CCR2, this chemokine orchestrates an excessive inflammatory response by recruiting leukocytes into the lung tissue and, therefore, driving the progression of COVID-19 to critical lung injury." (PMID 38455043, 2024). "The CCL2-CCR2 axis contributes to an immunosuppressive TME; thus, antagonistic drugs targeting CCR2 may be beneficial for cancer therapy or decrease undesired immune responses in COVID-19 and autoimmune diseases (i.e., nonalcoholic steatohepatitis)." (PMID 37198402, 2023). "A higher dose than what has been used in NASH could potentially be advantageous in COVID-19 patients, as this might ensure faster CCR2 and CCR5 inhibition (i.e., target engagement) of CVC." (PMID 35749425, 2022). "Furthermore, there was a trend towards lower frequencies of CCR2+ T cells in COVID-19 and in influenza." (PMID 35371005, 2022). "Furthermore, we observed reduced expression of CCR1 and CCR2 on monocyte subsets from individuals recovered from severe COVID-19." (PMID 36433939, 2022). "Targeting airway-derived cytokines, such as CCL2, via a CCR2 antagonist may be effective in reducing lung damage and preventing further respiratory sequelae in severe COVID-19." (PMID 35749425, 2022). "Individual genes associated with the COVID-19/sepsis shared hypermethylated and hypomethylated CpG genes include type I IFN-related genes, like IRF2, and others, such as IL1A and CCR2, that are involved in inflammatory processes and monocyte chemotaxis, respectively." (PMID 36443794, 2022). "Our results confirm CCR2 gene expression in PBCs could be considered a prognosis marker of COVID-19 evolution, as it was found increased only in those patients that developed critical illness." (PMID 36009555, 2022). "‘Interleukin-10 signalling’ pathway variants in IL10RB, CCR2 and CCR5 were also enriched in PRSe2 and may contribute to the development of severe COVID-19." (PMID 35770811, 2022). "CCL2/CCR2 are critical for monocyte and macrophage migration, a potential mechanism may be monocyte infiltration into the lungs via airway specific expression of CCL2/CCR2 in patients with severe COVID-19." (PMID 35749425, 2022). "Chemokine receptors, such as CCR9, CXCR6, CCR1, CCR3, CCR5, and CCR2, are all located on chromosome 3 and already showed significant associations with COVID-19 without network boosting." (PMID 36291657, 2022). "Given the adverse cardiovascular-related events seen in COVID-19, blockade of CCR2 could potentially reduce these adverse outcomes by decreasing the amount of circulating and infection site accumulation of inflammatory monocytes and other myeloid populations." (PMID 35749425, 2022).
COVID-19 (continued). "Interestingly, CD14highCD16− monocytes from COVID-19 patients also showed downmodulation of CCR2 and HLA-DR molecules when compared to HCs (respectively)." (PMID 35095880, 2021). "Marked phenotypic differences were observed in the monocytic compartment in COVID-19 patients, namely, a striking shift towards the CD14highCD16− classical/inflammatory monocyte subset and downmodulation of HLA-DR and CCR2 markers in those cells as reported in other studies." (PMID 35095880, 2021). "Interestingly, post-COVID-19 monocytes showed the highest expression of CCR2, CCR5, CD86 and HLA-DR, and the lowest of CD11b." (PMID 34572439, 2021). "By blocking the CCR2 and the CCR5 pathways, it is anticipated that the administration of CVC may be beneficial in potentially preventing or reversing the pulmonary and vascular sequelae associated with COVID-19." (PMID 35749425, 2022). "Individuals that suffered from severe COVID-19 show reduced frequencies of T cell, mucosal-associated invariant T cell (MAIT) and dendritic cell (DC) subsets and altered chemokine receptor expression on several subsets, such as reduced levels of CCR1 and CCR2 on monocyte subsets." (PMID 36433939, 2022). "Cenicriviroc, an inhibitor of CCR2/CCR5, demonstrated good efficacy in a phase II clinical trial for COVID-19." (PMID 38730482, 2024). "Indeed, CCR5 and CCR2 have interrelated pharmacologies in immune signaling, particularly for the inhibitory myeloid compartment, which may overcome potential interreceptor redundancy or enable a synergistic effect in limiting COVID-19 adverse immunopathology." (PMID 35749425, 2022). "Thus, altered expression of CCR1 and CCR2 at steady state might influence the severity of COVID-19." (PMID 36433939, 2022). "This article reviews the literature surrounding the CCR2 and CCR5 pathways, their proposed role in COVID-19, and the potential role of CVC to improve outcomes." (PMID 35749425, 2022). "In contrast, CXCR6, CCR2, and CCR5 were most highly expressed on TEM cells both in healthy controls and COVID-19 patients." (PMID 35371005, 2022). "Together, these results support a specific role for monocyte/macrophage immunopathology in COVID-19 and prioritize the investigation of MCP-3/CCR2 and CSF-1 signaling as therapeutic targets." (PMID 34710339, 2022). "Multiple studies have reviewed the roles of CCR2 and CCR5 in mediating respiratory and vascular sequelae across various diseases including COVID-19." (PMID 35749425, 2022). "Here, we compared changes in NK cell and T cell subset compositions, focusing on expression of the lung-homing receptors CXCR3, CXCR6, CCR2, and CCR5, in the peripheral blood from patients with clinically moderate COVID-19 or influenza." (PMID 35371005, 2022). "When compared to HC, monocytes from acute COVID-19 patients had higher size (FSC) and granularity (SSC), higher expression of CD11b, CD16 and CD33, similar expression of CCR2, CCR5 and CD86, and a marked downregulation of HLA-DR, as previously reported." (PMID 34572439, 2021). "This corroborates with our data where, contrary to CCL2, serum CX3CL1 was quicky augmented suggesting that non-classical monocytes (NC; CD14+/-CD16++/CX3CR1+) rather than classic monocytes (CL; CD14++CD16−/CCR2+) are the first actors during COVID-19." (PMID 40710346, 2025). "IL-6/JAK–STAT3 inhibitors, IL-1 blockers, and strategies targeting CCR2/CCR5 are under investigation in oncology and may, with careful selection, have dual relevance in patients with prior severe COVID-19 and inflammation-dominated tumor microenvironments." (PMID 41440526, 2025). "Individuals that suffered from severe COVID-19 showed reduced frequencies of T cell, MAIT cell and dendritic cell (DCs) subsets and altered chemokine receptor expression on several subsets, such as reduced levels of CCR1 and CCR2 on monocyte subsets." (PMID 35291290, 2022).
COVID-19 (continued). "However, classical and intermediate monocytes from individuals recovered from severe COVID-19 had reduced expression of pro-inflammatory chemokine receptors CCR1 and CCR2 (Bonferroni-adjusted P-value range 0.03–2.07 × 10−9)." (PMID 36433939, 2022). "Inhibiting the CCR2 and CCR5 pathways could attenuate or prevent inflammation or fibrosis in both early and late stages of the disease and improve outcomes of COVID-19." (PMID 35749425, 2022). "As inflammation and cytokine (including chemokine) release can occur via similar receptor pathways in pulmonary injury and SARS-CoV-2, we reviewed the literature surrounding the CCR5 and CCR2 pathways and the rationale for CVC as a potential agent in the treatment of patients with COVID-19." (PMID 35749425, 2022). "Additionally, we found that PCs in patients with severe COVID-19 had higher expression levels of inflammation genes (TNFSF10, S100A9, and S100A8) and chemokine-related genes (CCR2 and ITGB7) than those in patients with mild COVID-19." (PMID 33936072, 2021). "While increased CD38 expression across monocyte subsets was a general feature unrelated to disease severity, higher levels of CCR2 on iMonos, as well as lower levels of HLA-DR and CD86 with increased expression of CD163 in all monocyte subsets, were found in severe COVID-19." (PMID 33479167, 2021). "Therapeutic strategies to balance the positive and negative effects of CCR2 signaling may benefit the management of COVID-19 patients." (PMID 36239699, 2022). "Similarly, a clustering pattern of acute-phase COVID-19 non-classical monocytes upon bacterial challenge was characterized by an increased expression of CCR2, CD163 CD120b, CD11b and low expression of HLA-DR." (PMID 35007290, 2022). "We found that similar to monocytes CCR2 and CXCR3 were upregulated in DC3 of COVID-19 patients suggesting that DC3 together with monocytes may be recruited from the circulation to the infected lung in response to a gradient of CCL2 and CXCR3 ligands CXCL9/10/11." (PMID 34614036, 2021). "Expression levels of the receptor of MCP-1, C-C motif receptor 2 (CCR2); the receptor for IP-10, chemokine (C-X-C motif) receptor 3 (CXCR3); and the receptor for IL-8, CXCR2 were assessed in the PBMCs from severe or mild COVID-19 patients compared to those from healthy controls." (PMID 33413449, 2021). "Together, these results demonstrate common activation patterns between NK cell subsets in COVID-19 and influenza patients, with a stronger activation of NK cells expressing CXCR3, CXCR6, CCR2, and/or CCR5 than NK cells lacking any lung-homing receptors." (PMID 35371005, 2022).
prostate carcinoma (61 papers, 2011 to 2025). A carcinoma that arises from epithelial cells of the prostate gland. "Upregulation of CCL2/CCR2 and various immune conditions in prostate cancer are associated with cancer progression, metastasis, and relapse." (PMID 38468260, 2024). "CCR2 protein expression was detected in prostate cancer cells and was associated with prostate-specific antigen serum concentration (p = 0.045)." (PMID 39199567, 2024). "Previous research has shown that an upregulation of the ratio of CCL2 to it receptor (CCL2/CCR2) in another hormonally-responsive cancer - prostate cancer - was associated with advancement of disease, metastasis and relapse." (PMID 37181043, 2023). "We identified HOXB13 as an upstream regulator of HOXA11-AS, and found that HOXA11-AS regulated the CCL2/CCR2 signaling associated with prostate cancer bone metastasis." (PMID 33514011, 2021). "The up-regulation of CCL2/CCR2 and varied immune conditions in prostate cancer, are associated with cancer advancement, metastasis, and relapse." (PMID 32471499, 2020). "Transcription factor homeobox B13 (HOXB13) was identified as an upstream regulator of HOXA11-AS.HOXA11-AS regulated bone metastasis-associated C-C motif chemokine ligand 2 (CCL2)/C-C chemokine receptor type 2 (CCR2) signaling in both PC3 prostate cancer cells and SaOS2 osteoblastic cells." (PMID 33514011, 2021). "Analysis of real-time PCR and IHC staining on tissue microarray specimens revealed that higher CCR2 expression was also associated with higher Gleason score and higher clinical pathologic stages, suggesting a positive association between CCR2 expression and prostate cancer progression." (PMID 32471499, 2020). "On one hand, CCR2 expression promotes tumor associated macrophages (TAMs) and fibroblast recruitment at the primary tumors, where they enhance invasion, angiogenesis and metastasis of breast, glioma, lung and prostate cancer, melanoma, and multiple myeloma." (PMID 30591657, 2018). "A central role of CCR2 in TAM accumulation is supported by data showing high levels of tumour-derived CCR2 concurrent with leukocyte recruitment in several cancer types, including mammary, pancreatic, and prostate carcinoma." (PMID 40385641, 2025). "In prostate cancer, it was shown that the expression of CCR2 in a prostate cancer cell line correlated with cell migration towards dorsal root ganglion that expressed CCL2." (PMID 39199567, 2024). "CCR2 is generally considered to have a detrimental role in various cancers, particularly in prostate cancer." (PMID 38755605, 2024). "The chemokine C-C motif ligand 2 (CCL2) and its receptor C-C motif chemokine receptor 2 (CCR2) are expressed in prostate cancer but their prognostic value is unclear." (PMID 39199567, 2024). "Clinical trials have explored the use of anti-MCP-1 antibodies or CCR2 antagonists, showing promising results in treating breast and prostate cancers 105,114,115." (PMID 39132165, 2024). "CCL2 and CCR2 protein expression in prostate cancer biopsies at the time of diagnosis were quantified by immunohistochemistry and digital quantification." (PMID 39199567, 2024). "The interaction between CCL2 and CCR2 was reported to promote prostate-cancer cell migration via increased αvβ3 integrin production." (PMID 36289628, 2022). "CCL2 is a prominent modulator of bone metastatic growth of prostate cancer, it promotes cell proliferation, invasion, and migration by binding to CCR2 in both autocrine and paracrine manners." (PMID 33514011, 2021). "The activation of CCR2 is involved in resistance to regorafenib, a multikinase inhibitor, and cabazitaxel in colon and prostate cancer cells." (PMID 33406639, 2021). "Taken together, these data suggest that HOXA11-AS is an upstream regulator of CCL2/CCR2 signaling in both prostate cancer cells and osteoblastic cells." (PMID 33514011, 2021).